CHKA (choline kinase alpha)
Diseases named in the same sentence as CHKA in open-access papers (continued):
Sharing a sentence is not in itself a finding about the gene and the disease.
tumor (continued). "Furthermore, CHKA mRNA expression is higher in multiple tumor types compared to normal tissue." (PMID 27206796, 2016). "The enhancement of cisplatin sensitivity upon CHKA knockdown in tumor cells might open promising clinical perspectives providing a chance for increasing the treatment efficacy by allowing reduction of the dose of administered drugs and limiting unwanted effects on normal cells." (PMID 25796169, 2015). "CHKA has a key role in phospholipid biosynthesis and may contribute to tumour cell growth." (PMID 23382691, 2013). "CQ specifically binds to CHKA, inhibits its expression and enzymatic activity, and downregulates the downstream phosphorylation of PI3K and AKT, thereby suppressing tumor cell proliferation and inducing apoptosis." (PMID 39990656, 2025). "In order to further investigate the roles of CHKA in ATP8B1-related carcinogenesis and tumor progression, we then interfered with the CHKA gene via siRNAs in H520SH-ATP8B1 cells." (PMID 35159102, 2022). "Differential expression of seven of these genes (CFD, ALDH18A1, CHKA, DDIT3, ITGA6, PSPH and SQLE) was replicated in another set of 12 paired NASH-HCCs and adjacent non-tumor livers by RT-qPCR (all P < 0.05 by paired t test)." (PMID 30367044, 2018). "In addition, immunohistochemical staining and Western blot analysis further confirmed the inhibitory effect of CQ on the expression of CHKA and PFKM proteins in tumor tissues." (PMID 39990656, 2025). "SLC6A8 showed a consistent protein expression pattern, but not mRNA expression pattern, compared to the tumor tissue data, while CHKA did not." (PMID 40903981, 2025). "We demonstrated that dandelion extract could interfere with glycerophospholipids and unsaturated fatty acids metabolism by inhibiting CHKA/PI3K/AKT/FADS2 axis, ultimately resulting in the blockage of cell membrane formation and tumor cell death." (PMID 36147318, 2022). "In this study, the network pharmacology analysis spectacled that CHKA may interact with the P13K/AKT pathway, which is abnormally active in various tumor cells and is closely related to tumor growth, proliferation, and metabolism." (PMID 36147318, 2022). "Based on the KEGG enrichment in network pharmacology, CHKA might interact with the PI3K/AKT pathway, which plays a vital role in tumor growth, proliferation, and metabolism." (PMID 36147318, 2022). "Decreased CHKA protein expression was also confirmed by Western blot analysis in Raji tumour tissue obtained from AZD3965-treated mice, in concordance with the decline in tumour PCho content following drug treatment." (PMID 31937921, 2020). "Our results provide the first evidence that increased CHKA expression contributes to aggressive behaviors of CRC cells and correlates with tumor progression and metastasis and may serve as an independent unfavorable prognostic indicator for CRC patients." (PMID 27556502, 2016). "Given that increased CHKA expression in CRC is a common molecular incident and correlated with aggressive tumor characteristics, we hypothesize that depletion of CHKA can exert inhibitory effects on CRC development and progression." (PMID 27556502, 2016). "Inhibition of choline kinase alpha (CHKA), the first committed step to phosphatidylcholine synthesis, by the selective small-molecule ICL-CCIC-0019, potently suppressed growth of a panel of 60 cancer cell lines with median GI50 of 1.12 μM and inhibited tumor xenograft growth in mice." (PMID 27206796, 2016). "In the present study, we reported that CHKA protein expression was upregulated in CRC tissues and CRC-derived cell lines and was significantly correlated with several important clinicopathologic parameters including lymph node metastasis, tumor stage, disease recurrence and vital status." (PMID 27556502, 2016).
tumor (continued). "The results indicated that CHKA downregulation decreased the ECAR of Caco2 cells, and the addition of PCho significantly provided anaplerosis for the glycolysis in Caco2-shCHKA cells, suggesting that inhibition of the PI3K/AKT pathway could efficiently block the Warburg effect in tumor cells." (PMID 39990656, 2025).
infection (1 paper, 2024). The state of being infected such as from the introduction of a foreign agent such as serum, vaccine, antigenic substance or organism. "The result showed that during ALV-J infection, the levels of ASAH1, NAAA, CHKA, PGS1, SGPP1, DEGS2, and SMPD1 genes were significantly increased with infection time." (PMID 38598912, 2024).
retinopathy (1 paper, 2025). "To further explore the role of CHKA in pathological angiogenesis, we examined retinal flat mounts from oxygen‐induced retinopathy (OIR) model." (PMID 40548950, 2025).
CHKA also shares sentences with these, for which no sentence is quoted: breast tumor (3 papers); hepatocellular carcinoma (2); neurodevelopmental disorder (2); acute lymphoblastic leukemia (1); bacterial infections (1); breast adenocarcinoma (1); Burkitt lymphoma (1); colitis (1); colon adenocarcinoma (1); depression (1); dysplasia (1); esophageal cancer (1); gastric cancer (1); glioblastoma (1); gynecological tumor (1); Hypoglycemia (1); Insulin resistance (1); kidney damage (1); leukemia (1); leukodystrophy (1); lung squamous cell carcinomas (1); lymph node metastasis (1); memory impairment (1); myeloma (1); nephromegaly (1); non-small cell lung carcinoma (1); osteosarcoma (1); prostatic intraepithelial neoplasia (1); pulmonary fibrosis (1); schizophrenia (1).
A further 3 diseases each share a sentence with CHKA in 1 paper.